RN7SKP253 (RN7SK pseudogene 253)
Gene: Miscellaneous RNA gene on chromosome 4 (139,794,125 to 139,794,433, reverse strand). Ensembl gene ENSG00000252233.
Homologues: Orthologues: chimpanzee 7SK (99% identical), mouse Gm55684 (37% identical). Paralogues in human: RN7SKP217 (53% identical), RN7SKP151 (51% identical), RN7SKP184 (51% identical), 7SK (51% identical), RN7SKP133 (51% identical), RN7SKP118 (50% identical), RN7SKP162 (50% identical), RN7SKP230 (50% identical), RN7SKP124 (50% identical), RN7SKP47 (50% identical), RN7SKP77 (50% identical), RN7SKP187 (50% identical), and 284 more.